CD1A (CD1a molecule)
Diseases named in the same sentence as CD1A in open-access papers (continued):
Sharing a sentence is not in itself a finding about the gene and the disease.
tumor (continued). "Multiple regression models revealed CD1a+ DCs in the TC and PT region as the strongest predictors for densities of CD208+ cells in the tumor interior of synchronous LM." (PMID 41410751, 2025). "Due to the suspicion of bone marrow (BM) infiltration associated with moderate anemia, a BM trephine biopsy was requested, confirming patchy interstitial infiltrations of histiocytes with CD1a, CD68, and S100 positivity in the tumor cells." (PMID 39081692, 2024). "In a study of tumor cells from 48 DLBCL patients, it was found that in 21% of patients, there was an increased number of CD1a+ dendritic cells at the tumor margins, and this was significantly correlated with a favorable prognosis (p = 0.015)." (PMID 39834804, 2024). "For this purpose, we performed in a collective of OSCC a clinical data collection as well as immunohistochemical staining of some of the most important tumor-infiltrating immune cells, i.e., CD4+, CD8+, and FoxP3+ T-cells as well as CD1a+ DCs." (PMID 37345025, 2023). "We describe a unique tumor-infiltrating immune profile with high levels of lymphocytes (CD4, FOXP3) and dendritic cells (CD21, CD1a and CD83) that are valuable prognostic factors in post-NAC TNBC patients." (PMID 36765559, 2023). "Consistent with its promising features as selective T-ALL therapeutic target, recently an anti-CD1a CAR-T was developed, showing significant in vitro and in vivo anti-tumor effects." (PMID 35740552, 2022). "To sum up, we conclude that CD1a+ DCs show protective activity against cancer progression while CD1c+, DC-LAMP+ and DC-SIGN+ subsets favor tumor spread." (PMID 35955602, 2022). "This pattern of expression makes the targeting of CD1a fratricide-free and with limited on-target off-tumor effects supporting the idea of a personalized immunotherapeutic option for that sub-population of T-ALL patients, even rarely expressing CD1a." (PMID 35740552, 2022). "We also validated the significant relationship between galectin-9 expression and the previously established DC and T-cell activation-related factors, antigen-presenting cells, tumor infiltrating lymphocytes, and DC markers (CD208 as mDC and CD1a as imDC)." (PMID 36527024, 2022). "CD1a+ and CD207+ cells were observed throughout the epithelium, while, in the connective tissue, they were more prevalent in the tumor nests of the OSMF-OSCC and OSCC lesions." (PMID 31880289, 2020). "For this purpose, the tumour cells were stained with antibodies to CRT (red) and the DCs stained with a monoclonal antibody to the CD1a activation marker (green)." (PMID 31558803, 2019). "Lymphocytes within the tumor expressed CD4, CD8, TdT and CD1a, a pattern consistent with thymocytes." (PMID 31639039, 2019). "Future studies should however focus not only on the presence of tolerogenic immature CD1a+ DCs in tumour tissue, but also on their functional phenotype, as this may add important information on their potential immune modulatory effect in the inflammatory tumour microenvironment." (PMID 28673320, 2017). "Distribution densities of CD1A, IL-13 and CD68 in tumor stroma of 66 ESCC patients were further calculated with InFormTM 2.0.1 software." (PMID 26771842, 2016). "Distribution features of CD1A, CD123, CD57, CD66b, CD68 and IL-13 were detected in 20 ESCC patients’ tumor tissues with IHC staining." (PMID 26771842, 2016). "In contrast, GM-CSF+IL-4 conditioning leads to predominant migration of CD1a+ LC and DDC subsets in a sustained mature state that predominantly release IL-12p70 and can induce both Th1 and tumor-specific CD8+ high-avidity effector T cells." (PMID 23875023, 2013). "There was also a trend towards increased dendritic cell (PS100, CD1a) and HLA-DR-expressing cell infiltration in TAXHER01 tumours." (PMID 16404427, 2006). "The tumor cells consistently express S100 protein and vimentin and are negative for CD1a, Langerin (CD 207), CD21, CD23 and CD35." (PMID 40088330, 2025).
tumor (continued). "Studies which focused on CD1a-DCs infiltration into primary tumor and regional LNs were few in number and the evaluation methods of CD1a-DCs were not uniform." (PMID 39684473, 2024). "High CD1a levels have been associated with worse outcomes in TNBC, but no data are available in luminal tumours." (PMID 38473874, 2024). "This study investigated differences in clinical and pathological parameters as well as differences in the tumor immune microenvironment by immunohistochemical examination of tumor infiltration of CD4+, CD8+, FoxP3+, and CD1a+ cells in SD and NSND OSCC patients." (PMID 37345025, 2023). "It is interesting to notice that in this study the infiltration by CD1a+ immature DC in PCa samples was assessed by counting the number of positive cells in the tumor samples without taking into account the localization of the immune cells." (PMID 37435060, 2023). "Positive staining of melanin marker, CD34, CD1a, and SMA are helpful in diagnosing this tumor." (PMID 36800595, 2023). "Subsequently, pathological biopsy of the lymph nodes revealed high expression of CD163, CD68, S100, Lys and CD34 in the tumor cells and no expression of CD1a and CD207, confirming this rare clinical diagnosis." (PMID 36969238, 2023). "The CD1A, CD1B, GRP, SERPINE1, and F2RL2 genes were highly expressed in tumor tissue." (PMID 36221049, 2022). "Furthermore, we noted the positive correlation between numbers of immature CD1a+ and mature DC-LAMP+ DCs, implying distinct roles of DCs populations in lymphoid tissue or the primary tumor site." (PMID 35955602, 2022). "There were significant differences between low and high ANXA1 expression based on age (p = 0.002), tumour location (p = 0.001), recurrence (p = 0.048), WHO grade (p = 0.005), CD1a (p = 0.015) and PD‐L1 expression (p = 0.000); however, other parameters were not correlated with this difference." (PMID 35770335, 2022). "Immunohistochemically, tumor cells demonstrated membranous positivity for CD99, positivity for Nkx2.2, focal positivity for S100 and negativity for desmin, myogenin, MyoD1, cytokeratin (AE1/AE3), CD31, CD34, CD3, CD20, and CD1a." (PMID 34749732, 2021). "In BCC, the majority of LCs were located within the surface of the epidermis, and very few within and around tumour cords, while in SCC, an impressive number of positive anti-CD1a cells were found within the tumour, in contrast to the small number of labelled cells within surrounding tissue." (PMID 32377167, 2020). "A significantly higher number of CD1a-positive DCs was observed in the clinical parameters of tumor invasion in EBV-negative GC, but such a correlation was not identified in EBVaGC." (PMID 33198173, 2020). "The number of dendritic cells per tumor area was significantly higher in EBVaGC cases than in EBV-negative GC cases for any of the DC markers (p < 0.001 for Langerin, CD1a, CD83, CD86, and BDCA-2, and p < 0.05 for S100, respectively, determined by using a Wilcoxon rank sum test)." (PMID 33198173, 2020). "High density of CD1a+ DCs was an independent prognostic factor for a reduced OS in PB-type but not in I-type tumours (adjusted HR = 2.35; 95% CI 1.13–4.87)." (PMID 28673320, 2017). "The results demonstrate that high infiltration of CD1a+ TIDC is an independent predictor of a shorter survival in patients with PB-type tumours, but does not confer any prognostic value in patients with I-type tumours." (PMID 28673320, 2017). "We have shown that lactic acid, a side product of glycolytic energy production, accumulated in dense MoDC cultures and played an important role in reducing the development of IL-12-producing CD1a+CD14− DCs16, similarly as it has previously been shown in MoDCs developing in tumour microenvironment." (PMID 28276533, 2017). "Tumor cells were commonly positive for TDT (21/26, 80.8%), CD3 (29/31, 93.5%), and CD7 (25/27, 92.6%), and they were variably positive for CD5 (16/24, 66.7%), CD99 (14/19, 73.7%), CD2 (12/18, 66.7%), and CD1a (13/21, 61.9%)." (PMID 28566711, 2017).
tumor (continued). "A significant treatment interaction between a high ratio of CD56+ NK/NKT cells in relation to the sum of CD68+ and CD1a+ cells were seen in the whole cohort (p = 0.007) and in PB-type tumours (p = 0.012), but not in I-type tumours (data not shown)." (PMID 27275582, 2016). "Whereas CCR6 seems to be required for retention of LCH-cells in the various tissues, our in vitro experiments support a role for CXCR4 in the distribution of blood-borne CD1a+CD11c+CXCR4+‘LCH-cell like’ myeloid cells in analogy to both immune cells and tumor cells." (PMID 28255525, 2016). "In our previous studies, we found that IL-17A could mediate anti-tumor immunity by recruiting immune cells to the tumor microenvironment, such as NK cells, CD8+ T cells and CD1a+ DCs." (PMID 26942702, 2016). "The specific trigger for decreased CD1a expression in our studies is not known, but tumor-derived factors such as prostanoids and gangliosides are known to inhibit CD1a expression." (PMID 25886502, 2015). "The changes to iMoDC surface phenotype are likely to be tumor-driven, as exposure to Met5A cells did not alter the percent of CD1a+, CD86+ or CD80+ iMoDCs, nor did it alter surface expression levels (MFIs) of CD86 or CD80 on iMoDCs, relative to DCs only." (PMID 25886502, 2015). "We found that CD1a- and CD83-positive cells were dispersed with variable density and in OC CD31+ vessel numbers were positively correlated with CD83+ dendritic cells in tumour stroma (R = 0.847, p = 0.016)." (PMID 26019537, 2014). "The immunohistochemistry staining showed that the tumor cells were diffusely positive for S-100, CD1a, langerin and CD68, but negative for CD3, CD5, CD20, CD21, CD30, CD38, CD56, CD79a, ALK, HMB-45, Melan-A, pan-cytokeratin and MPO." (PMID 23388086, 2013). "Since dermal (interstitial) DCs were found in vitro and in vivo to express CD1a, but not Langerin, we currently conclude that CD1a+/Langerin- tumour-infiltrating DCs represent immature interstitial DCs." (PMID 20969772, 2010). "The immaturity of CD1a+ DCs within the tumour tissue was further demonstrated by the absence of maturity markers, such as DC-LAMP, CD40, or RelB expression, as assessed by serial analyses in confocal microscopy of double fluorescence-stained sections." (PMID 20969772, 2010). "Our findings in this study addressed this issue and showed that the density of tumour infiltrating CD1a+ dendritic cells did not significantly correlate (at the P=0.05 level) with overall survival at the 5-year time point following surgery." (PMID 12888826, 2003). "Notably, CD1a+ cells showed TLR7 expression only when they were infiltrating the tumor, but not in the stroma." (PMID 39849091, 2025). "The tumor typically shows positivity for S-100 protein and CD1a but is negative for CD207/langerin." (PMID 38713245, 2024). "Although higher levels of CD1a+ DCs were present in tumor-positive LN (LN+) as compared to tumor-negative LN (LN−), these cells might have been derived from recruited and tumor-converted monocytes rather than conventional migratory CD1a+ DC." (PMID 30944963, 2019). "By IHC staining her tumor was CD1a, CD68, and S-100 positive and negative for CD30." (PMID 25405526, 2014). "CD1a+ DC may not have the capacity to adequately mature, and present antigen within the tumour microenvironment, or may become inhibited." (PMID 12888826, 2003). "It was also possible that CD1a negative DC may have been present and active within the tumour microenvironment." (PMID 11870535, 2002). "In particular, its overexpression by axillary lymph nodes could prevent lymph node metastases; nevertheless, the authors of this work found a higher number of mature CD83-positive DCs, but not of immature CD1a-positive DCs, in tumour-free sentinel lymph nodes than those containing tumours." (PMID 15756258, 2005).
tumor (continued). "Immunohistochemical staining for CD1a and CD208 was performed on non-tumor adjacent mucosa (NAM), as well as tumor center (TC), inner margin (IM), outer margin (OM), and peritumoral zone (PT) of both pCRC and LM." (PMID 41410751, 2025). "Finally, although CD1a/CD208 immunophenotyping captured the most relevant DCs maturation dynamics in this study, we did not assess other myeloid populations that may participate in interactions between the tumor and the immune system, which should be addressed in future studies." (PMID 41410751, 2025). "DC cocultured with UVM cells showed reduced expression of CD1a and CD83, which failed to activate T cells for immune response, revealing the possibility of tumor-pulsed dendritic cell vaccines as therapeutic measures for UVM." (PMID 36568076, 2022). "Our data showed no influence on tumor infiltration by mature (CD83+) and immature (CD1a+) DCs on the survival of patients with TSCC." (PMID 35584505, 2022). "Compared with follicular dendritic cells and Langerhans cells of the same family, tumor cells are negative for CD21, CD23, CD35, D2–40, CD207, CD1a, and CK." (PMID 33655917, 2021). "It was not possible to analyze the tumor to stroma ratio of mDCs, nor of CD208+CD15+ and CD1a+CD15+ granulocytes, due to the paucity of these cell populations." (PMID 33013928, 2020). "We found statistically more in situ CD3+ T cells in tumor negative vs. tumor positive nodes (mean of 8878 vs. 6704, respectively, p = 0.006), but no statistical difference in CD20+ B cells or CD1a+ dendritic cells." (PMID 30155518, 2018). "The tumor cells were negative for CD21, CD23, CD35 and CD1a, CKpan, cam5.2, EMA, HMB45, Melan A, CD3, CD20, Desmin, SMA, and so on." (PMID 28386111, 2017). "Immunohistochemistry revealed that these tumor cells were positive for microphthalmia-transcription factor, S100, and CD1a but negative for HMB45, indicating that the tumor was a CCST." (PMID 27871249, 2016). "Immunohistochemically, the tumor cells showed positive for vimentin and CD68, while stains for CK, CK8/18, CD35, CD21, CD1a, S-100, HMB45, MelanA, SMA, LCA were all negative." (PMID 22221822, 2012). "Although double staining immunohistochemistry was not performed, with the extensive degree of staining with CD1a, S100, langerin, CD3 and CD30, the tumor cells were interpreted as positive for all these markers." (PMID 23006414, 2012). "Further literature analysis indicated the nonspecificity of symptoms in patients with this tumor localization and variability in CD45 and CD68 staining in tumor cells, with consistent lack of expression of CD21, CD23, CD35, CD1a, and specific T- and B-cell antigens." (PMID 39171855, 2026). "Immunohistochemically, tumor cells diffusely expressed cytokeratins, vimentin, CD68, CD163, and EMA, with focal expression of SMA, S-100, calponin, and CD3, but were negative for CD21, CD35, CD1a, ALK, and HHV8." (PMID 42311660, 2026). "The tumor cells were robustly and diffusely positive for Trk, S100-protein, CD34, and nestin, but negative for CD56, SMA, desmin, myogenin, STAT6, EMA, CK, CD1a, CD21, CD35, CD43, WT-1(c-terminal), MelanA, HMB45, BRAF, and ALK." (PMID 32957984, 2020). "This tumor was classified as an undifferentiated myxoid sarcoma based on the lack of a glial proliferation, strong CD68 and vimentin immunolabeling in the majority of tumor cells and the absence of CD1a and GFAP immunolabeling." (PMID 24073000, 2013).
cancer (40 papers, 1999 to 2025). A tumor composed of atypical neoplastic, often pleomorphic cells that invade other tissues. "Another explanation is the possible difference in percentages of the glandular epithelium—linked with DC CD1a+ numerosity—between cancers from different groups." (PMID 36768258, 2023). "CD1A has previously been implicated with cancer development, with expression and positive correlation to survival reported for some cancer types." (PMID 28362259, 2017). "Infiltrating CD1a+ dendritic cells (DCs) have been associated with increased survival in a number of human cancers." (PMID 12888826, 2003). "Among the dendritic cell subset markers of the monocyte-derived dendritic cells, it is noteworthy that CD1A mRNA counts were also found to be associated with the risk of relapse and cancer progression, while CD209 was associated only with an increase in SPP1 levels." (PMID 38275392, 2023). "Furthermore, DC numbers, as measured using either CD1a or S-100 antibodies, have been positively associated with improved outcome (increased survival) for many of these cancers, although the mechanism remains unclear." (PMID 12888826, 2003). "Therefore, the analysis of various cytokines and chemokines in cancer tissue that are associated with the infiltration and maturation of DCs is an important research area, as well as the examination of the characteristics of CD1a-DC regarding their interaction with cancer cells." (PMID 38396770, 2024). "Patients’ ages in this group were significantly lower than in cancers with higher counts of CD1a-positive cells in EC glands (group 3)." (PMID 36768258, 2023). "We found a significant divergence of grade value distribution between cancers of different DCs’ CD1a+ counts." (PMID 36768258, 2023). "Contrary to this, cancers with the most numerous DC CD1a+ (group 4) in the glandular epithelium comprised relatively young patients." (PMID 36768258, 2023). "In this study, cancers with the least numerous DC CD1a+ on their infiltrative borders had statistically higher grade scores than ones with higher DC counts." (PMID 36768258, 2023). "Densities of CD1a+ cells in distant area of SLNs were significantly higher in G1 (66.53 ± 19.46, p < 0.020) and G2 (63.48 ± 32.26, p < 0.035) than in G3 cancers (45.60 ± 30.12)." (PMID 35955602, 2022). "We do know, however, that CD1a expression is altered in several disease models, including aberrant expression in cancers such as hairy cell leukemia and some T lymphoblastic lymphomas." (PMID 34956202, 2021). "CD1a-positive DCs have been widely investigated in various human cancers with results varying between papers." (PMID 28331853, 2017). "Analysis of leucocytes from colons of UC identified monocytes, and CD1a+ CD11b+ macrophages and NK T-cells as significantly different in comparison to normal tissue derived from cancer patients undergoing colectomy." (PMID 27809916, 2016). "It was originally assumed that the neoplastic transformation responsible for cancer development in LCH occurs within CD1a+CD207+(Langerin+) LCs in the skin." (PMID 26459350, 2015). "The number of CD1a+ DCs in both locations was the highest in luminal B/HER2+ cancers." (PMID 33919875, 2021). "A possible explanation of the correlation of the adverse effect of CD1a+ DCs is that CD1a+ DCs have a specific but unknown function other than antigen presentation that accelerates the progression of cancer cells." (PMID 34461859, 2021). "However, expression of CD1d on moDC has been shown to be negatively correlated with expression of CD1a, which in turn has been suggested to be a surrogate marker for IL-12 secreting type-1 polarized moDC, the preferred functional characteristics for cancer vaccines." (PMID 26460687, 2015). "From our best research, HOXC6, SLC2A4, VIP, CD1A, STC2, and OLFM2 are related to cancer progression." (PMID 35711425, 2022).